MIR1587 (microRNA 1587)
Synonyms: hsa-mir-1587
Gene: MicroRNA gene on chromosome X (39,837,561 to 39,837,613, forward strand). Ensembl gene ENSG00000263972.
Homologues: Orthologues: chimpanzee MIR1587 (100% identical).